BMI1 (BMI1 proto-oncogene, polycomb ring finger)
Diseases named in the same sentence as BMI1 in open-access papers (continued):
Sharing a sentence is not in itself a finding about the gene and the disease.
pancreatic cancer (continued). "After Bmi1 was inhibited, Transwell assays showed that the migration and invasion of pancreatic cancer cells were reduced by gemcitabine and low-dose VPA separately and combined therapy." (PMID 31244991, 2019). "Previous study showed that endogenous expression of Bmi1 promotes invasion and progression in pancreatic cancer." (PMID 31088566, 2019). "We found that Bmi1 siRNA knockdown remarkably decreased Bmi1 expression at mRNA and protein levels in two pancreatic cancer cell lines in hyperglycemic medium." (PMID 31088566, 2019). "In current study, we confirmed that Bmi1 can inhibit anticancer immunity of pancreatic cancer via reducing NK cell killing through suppressing MICA/B expression." (PMID 31088566, 2019). "Knocking down Bmi1 in pancreatic cancer cells suppressed the migration and invasion induced by VPA and gemcitabine cotreatment." (PMID 31244991, 2019). "In this study, we determined the influence of Bmi1 on immunological characteristics of pancreatic cancer." (PMID 31088566, 2019). "Pancreatic cancer cells with Bmi1 overexpression were co-cultured with NK cells, and the killing effect was detected using LDH release assay." (PMID 31088566, 2019). "B, C, MICA/B expression in mRNA and protein levels in the presence of Bmi1 knockdown in both pancreatic cancer cell lines." (PMID 31088566, 2019). "Previous studies have found that Bmi1 plays a promoting role in gemcitabine-induced chemoresistance and migration in pancreatic cancer cells." (PMID 31244991, 2019). "We next examined the expression level changes of Bmi1, Nanog and Sox2 after gemcitabine treatment in pancreatic cancer cells with western blot analysis." (PMID 29018223, 2017). "In this context, Bmi1 was found to be overexpressed in the cancer stem cell compartment of primary human pancreatic cancer xenografts; in line with this observation, pancreatic tumorspheres were shown to possess high Bmi1 levels." (PMID 29156578, 2017). "Bmi1 was found to be overexpressed in PanIN lesions, pancreatic adenocarcinomas and pancreatic cancer cell lines." (PMID 29156578, 2017). "Taken together, our results suggested that Bmi1 promoted the chemoresistance of pancreatic cancer cells to gemcitabine." (PMID 27177084, 2016). "The endogenous expression of Bmi1 in pancreatic cancer has been reported to promote invasive and metastatic abilities in previous study." (PMID 27177084, 2016). "As a result, we detected increased ROS in pancreatic cancer cells treated with gemcitabine, and Bmi1 inhibition by siRNA transfection further enhanced ROS production." (PMID 27177084, 2016). "To explore the underlying mechanisms of enhanced ROS production after Bmi1 knockdown in pancreatic cancer cells, we compared the expression of antioxidant genes before and after Bmi1 siRNA transfection through quantitative real-time PCR." (PMID 27177084, 2016). "The abnormal expression of Bmi1 has been also reported to link disease progression and poor prognosis in pancreatic cancer patients." (PMID 27177084, 2016). "We then compared the sensitivity of pancreatic cancer cells to gemcitabine in combination with Bmi1 inhibition." (PMID 27177084, 2016). "To explore the potential role for Bmi1 towards chemotherapy, we detected the changes of Bmi1 expression in pancreatic cancer cells treated by gemcitabine." (PMID 27177084, 2016). "In this study, we found that certain dose of gemcitabine treatment induced Bmi1 expression in pancreatic cancer cells." (PMID 27177084, 2016). "To further explore the mechanisms of increased apoptosis of pancreatic cancer cells, we determined the Δψm of pancreatic cancer cells using a JC-1 method after gemcitabine treatment and Bmi1 inhibition." (PMID 27177084, 2016). "Gemcitabine has been proved to exert different effects on pancreatic cancer cells in a dose and time dependent manner by inducing different signaling pathways, whereas Bmi1 expression can also be affected by such specific signaling molecules." (PMID 27177084, 2016).
pancreatic cancer (continued). "Our results indicated that BMI-1 was a promising therapeutic target to inhibiting CSCs-mediated pancreatic cancer metastasis." (PMID 26840020, 2016). "Bmi1 inhibition also suppressed the activation of NF-κB signaling and the expressions of downstream molecules in pancreatic cancer cells treated with gemcitabine." (PMID 27177084, 2016). "In our study, Bmi1 inhibition aggravated the production of ROS in pancreatic cancer cells induced by gemcitabine treatment." (PMID 27177084, 2016). "Altogether, our results suggested Bmi1 knockdown inhibited the activation of NF-κB signaling cascade in pancreatic cancer cells treated with gemcitabine." (PMID 27177084, 2016). "Our results showed that Bmi1 inhibition sensitized pancreatic cancer to gemcitabine through aggravating oxidative stress and inhibiting NF-κB signaling." (PMID 27177084, 2016). "Knockdown of BMI-1 expression attenuated invasion ability of pancreatic cancer stem cells in Transwell system and liver metastasis capacity in nude mice which were injected CSCs through the caudal vein." (PMID 26840020, 2016). "We examined BMI-1 expression in five human pancreatic cancer cell lines, PanC-1, SW1990, Colo357, AsPc-1 and BxPc-3 using western blot." (PMID 26840020, 2016). "Bmi1 knockdown remarkably reduced Bmi1 protein level in both pancreatic cancer cells treated with gemcitabine." (PMID 27177084, 2016). "As shown in the result, ectopic expression of Bmi1 dramatically increased the IC50s of gemcitabine at 48 h and 72 h in two pancreatic cancer cells." (PMID 27177084, 2016). "BMI-1 was also up-regulated in pancreatic cancer cell lines and increased tumor cells invasion in vitro." (PMID 26840020, 2016). "In our study, the PANC-1 and ASPC-1 pancreatic cancer cell lines were treated with different concentrations of gemcitabine, the alterations of Bmi1 expression were determined by quantitative real-time PCR, Western blot and immunofluorescence." (PMID 27177084, 2016). "In our study, we found that a certain concentration range of gemcitabine promoted Bmi1 expression in pancreatic cancer cells." (PMID 27177084, 2016). "In order to determine the expression of Bmi1 and Ring1b and the presence of H2AK119ub in pancreatic cancer development, we took advantage of Ptf1aCre/+;LSL-KrasG12D/+;Trp53lox/+ (KPC) mice, which develop pancreatic cancer within a short time frame." (PMID 26716510, 2016). "For example, a report indicates that ZEB1 inhibits the expression of the miR-200 family, resulting in upregulation of polycomb protein Bmi1 and induction of stemness in pancreatic cancer." (PMID 25749385, 2015). "Holoclones and meroclones were positive for BMI-1, an oncogene suggested to play a role in stem cell self-renewal and which has been previously shown to be up-regulated in pancreatic cancer cell holoclones." (PMID 24587067, 2014). "High levels of Bmi1 expression were noted in BxPC3, Panc-1, AsPC-1, and Capan2 human pancreatic cancer cell lines, while expression was low in the MiaPaCa2 pancreatic cancer cell line." (PMID 23437065, 2013). "Bmi1 was overexpressed in the cancer stem cell compartment of primary human pancreatic cancer xenografts." (PMID 23437065, 2013). "We functionally validated the importance of Bmi1 expression in pancreatic cancer using pancreatic cancer cell lines and primary human tumor xenografts." (PMID 23437065, 2013). "Since our in vitro studies suggested that Bmi1 plays a regulatory role in pancreatic cancer cell proliferation and invasion, we wanted to address the biological significance of these results in an in vivo orthotopic model of pancreatic cancer." (PMID 23437065, 2013). "Bmi1 overexpression in MiaPaCa2 pancreatic cancer cells led to increased proliferation and enhanced invasion in in vitro Matrigel assays." (PMID 23437065, 2013). "Overexpression of Bmi1 was consistently observed in pancreatic cancer tissues compared with normal controls." (PMID 23437065, 2013).
pancreatic cancer (continued). "We asked if Bmi1 expression had such an effect in pancreatic cancer cells using the Matrigel in vitro invasion assay." (PMID 23437065, 2013). "Our results implicate Bmi1 in the invasiveness and growth of pancreatic cancer and demonstrate its key role in the regulation of pancreatic cancer stem cells." (PMID 23437065, 2013). "In this study, we examine the functional significance of Bmi1 expression in pancreatic adenocarcinoma using primary human xenograft models and pancreatic cancer cell lines." (PMID 23437065, 2013). "Given the increased level of expression of Bmi1 in pancreatic epithelial neoplastic tissue and its known cell cycle regulatory role, we next asked if its overexpression plays a functional role in pancreatic cancer cells." (PMID 23437065, 2013). "Our findings in human pancreatic cancer cell lines and primary human xenografts further extend these observations and implicate Bmi1 in inducing EMT and drug resistance thereby regulating pancreatic cancer growth and aggressiveness." (PMID 23437065, 2013). "Bmi1 was upregulated in pancreatic tumors arising in the Ela-tTa, TetO-Cre, KrasG12V genetically engineered mouse model of pancreatic cancer." (PMID 23437065, 2013). "Bmi1 was overexpressed in human PanINs, pancreatic cancers, and in several pancreatic cancer cell lines." (PMID 23437065, 2013). "Overexpression of Bmi1 has been noted in human pancreatic cancer samples compared to the normal pancreas." (PMID 23437065, 2013). "The present study provides clear evidence for the integral involvement of Bmi1 in the pathogenesis of pancreatic cancer." (PMID 23437065, 2013). "We first sought to determine the expression of Bmi1 in samples of human primary pancreatic cancers and compared expression levels to samples of normal pancreas." (PMID 23437065, 2013). "Our work reveals that Bmi1 supports human pancreatic cancer growth by regulating cell cycle progression and maintaining the pancreatic cancer stem cell compartment." (PMID 23437065, 2013). "Overexpression of Bmi1 has been correlated with worse prognosis in a small cohort of pancreatic cancer patients." (PMID 23437065, 2013). "We also examined five pancreatic cancer cell lines, MiaPaCa2, Panc-1, AsPC-1, BxPC-3 and Capan2 for the expression of Bmi1 using Western blot analysis." (PMID 23437065, 2013). "Most human pancreatic cancer cell lines were also observed to have high endogenous expression of Bmi1." (PMID 23437065, 2013). "We also assessed the cancer stem cell frequency, tumorsphere formation, and in vivo growth of human pancreatic cancer xenografts after Bmi1 silencing." (PMID 23437065, 2013). "Bmi1 silencing in PCSCs inhibited secondary and tertiary tumorsphere formation, decreased primary pancreatic tumor xenograft growth, and decreased the proportion of CSCs in the xenografts." (PMID 24325450, 2013). "For example, the STAT3/Bmi1 pathway could be modulated by VPA to increase the sensitivity of gemcitabine to pancreatic cancer cells." (PMID 34568018, 2021). "We found that Bmi1 overexpression inhibited NK cell killing in both pancreatic cancer cell lines." (PMID 31088566, 2019). "In this study, we identified a novel role of Bmi1 in pancreatic cancer immune escape." (PMID 31088566, 2019). "We further explored the effect of high glucose on Bmi1 expression in pancreatic cancer cells." (PMID 31088566, 2019). "Developing strategies for targeting Bmi1 may represent promising ways to promote the effects of chemotherapy on pancreatic cancer." (PMID 31244991, 2019). "Bmi1 overexpression was achieved by transfection of overexpression vector into pancreatic cancer." (PMID 31088566, 2019). "Moreover, lysis of pancreatic cancer cells by NK cells increased under high glucose after Bmi1 knockdown with siRNA transfection." (PMID 31088566, 2019). "Moreover, Bmi1 inhibits MICA/B expression through up-regulating of GATA2 in pancreatic cancer cells, contributing to the immune escape eventually." (PMID 31088566, 2019).
pancreatic cancer (continued). "Next, we investigated whether Bmi1 was involved in regulating GATA2 expression in pancreatic cancer cells." (PMID 31088566, 2019). "We are the first to reveal that BMI-1 could promote invasion and metastasis ability of pancreatic cancer stem cells." (PMID 26840020, 2016). "Moreover, the chemotherapeutic sensitivity of pancreatic cancer to gemcitabine can be increased by Bmi1 inhibition both in vitro and in vivo." (PMID 27177084, 2016). "However, the role of Bmi1 in response of pancreatic cancer cells towards gemcitabine resistance remains elusive." (PMID 27177084, 2016). "Furthermore, we also observed a decrease in NF-κB/p65 levels both in nuclear and cytoplasmic fractions of pancreatic cancer cells after Bmi1 inhibition by immunoblot analysis of subcellular fractionation." (PMID 27177084, 2016). "We found Bmi1 siRNA inhibited Bmi1 expression in both two pancreatic cancer cells effectively." (PMID 27177084, 2016). "Besides, we also found enhanced translocation of cytochrome C from mitochondria to the cytosol of pancreatic cancer cells treated with gemcitabine and Bmi1 siRNA." (PMID 27177084, 2016). "However, the role of Bmi1 in response of pancreatic cancer cells towards chemotherapy and subsequent chemoresistance remains elusive." (PMID 27177084, 2016). "We hypothesized that aberrant expression of Bmi1 might closely correlate to the sensitivity of gemcitabine treatment in pancreatic cancer cells." (PMID 27177084, 2016). "In our study, we found that Bmi1 might protect pancreatic cancer cells from oxidative stress through regulating a series of antioxidant enzymes." (PMID 27177084, 2016). "Correspondingly, we also verified the increased apoptosis of pancreatic cancer cells treated with gemcitabine combined with Bmi1 inhibition, and this enhanced apoptosis could be inhibited by ROS scavenger." (PMID 27177084, 2016). "The results indicated that Bmi1 may protect pancreatic cancer cells from apoptosis by removing excessive ROS induced by gemcitabine treatment." (PMID 27177084, 2016). "To further determine whether the enhanced sensitivity to gemcitabine after Bmi1 inhibition is correlated with the changes of NF-κB activity in pancreatic cancer cells, we compared the status of NF-κB in pancreatic cancer cells through EMSA." (PMID 27177084, 2016). "Moreover, this apoptosis and ROS production in pancreatic cancer cells was further increased with Bmi1 knockdown." (PMID 27177084, 2016). "Then, we found that BMI-1 expression was up-regulated in pancreatic cancer stem cells." (PMID 26840020, 2016). "Altogether, our data suggested that Bmi1 inhibition might promote the release of cytochrome c into the cytosol in gemcitabine-treated pancreatic cancer cells, leading to apoptotic cascade at least in part by enhancing ROS production." (PMID 27177084, 2016). "In summary, our findings indicate that BMI-1 could be used as the therapeutic target to inhibiting CSCs-mediated pancreatic cancer metastasis." (PMID 26840020, 2016). "We hypothesized that Bmi1 may play a functional role in these pancreatic cancer stem cells (CSCs) given its involvement in other stem cell systems." (PMID 23437065, 2013). "The finding of an essential role for Bmi1 in the regulation of cell cycle, growth, and invasion in pancreatic cancer as demonstrated in this study supports the possibility that Bmi1 regulates proliferative capacity in an INK4A-independent manner in pancreatic cancer." (PMID 23437065, 2013). "We therefore hypothesized that Bmi-1 might regulate resistance against chemotherapeutic agents in pancreatic cancer cells." (PMID 23437065, 2013). "It is difficult to extrapolate how Bmi1 expression in pancreatic cancer stem cells relates to normal pancreatic homeostasis as the only paper addressing Bmi1 function and not just expression in the adult pancreas focuses on a murine model and not human pancreas." (PMID 23437065, 2013).
pancreatic cancer (continued). "The high levels of Bmi1 expression seen in precursor lesions of pancreatic cancer (PanINs) also suggest that expression of Bmi1 occurs at an early stage in pancreatic oncogenesis and may potentially play a role in pancreatic cancer progression." (PMID 23437065, 2013). "Bmi1 induced MiaPaCa2 cells showed enhanced engraftment, with 100% (5/5) orthotopic tumor formation while only 3/5 mice injected with wild type MiaPaCa2 cells showed pancreatic tumor engraftment." (PMID 23437065, 2013). "Moreover, the STAT3/Bmi1 axis may be important downstream effectors determining the biological reactions of pancreatic cancer cells during chemotherapy." (PMID 31244991, 2019). "Moreover, low-dose VPA increased the reactive oxygen species (ROS) production, which activated AKT to further stimulate the activation of STAT3, Bmi1 expression and eventually promoted the migration and invasion of pancreatic cancer cells induced by gemcitabine." (PMID 31244991, 2019). "Taken together, our study demonstrated that Bmi1 could decrease the sensitivity of pancreatic cancer cells to gemcitabine through increasing oxidative stress and inhibiting NF-κB signaling, thus Bmi1 may serve as a promising target for sensitizing pancreatic cancer cells to chemotherapy." (PMID 27177084, 2016). "To assess the potential role of BMI-1 in regulation of invasion and metastasis ability of pancreatic CSCs and the underlying mechanism, we firstly investigated the association of BMI-1 and CSCs maker CD133 with clinicopathological parameters and survival of pancreatic cancer patients." (PMID 26840020, 2016). "Therefore, we have investigated the functional relevance of Bmi1 and Ring1b re-expression in ADMs and pancreatic cancer cells and identified changes of histone modifications at promoter sites of acinar differentiation genes in the sequence of pancreatic carcinogenesis." (PMID 26716510, 2016). "Thus, we hypothesized that Bmi1 may suppress the sensitivity of pancreatic cancer cells towards gemcitabine treatment via regulating oxidative stress and NF-κB activity." (PMID 27177084, 2016). "Bmi1 may participate in regulating the chemosensitivity of pancreatic cancer to chemotherapy." (PMID 27177084, 2016). "Thus, it is tempting to speculate that different signaling pathways induced by low or high concentrations of gemcitabine treatment may exert promoting or inhibiting role on Bmi1 expression in pancreatic cancer cells." (PMID 27177084, 2016). "The function of Bmi1 in pancreatic cancer was assessed by alteration of Bmi1 expression in several cell model systems by measuring cell proliferation, cell apoptosis, in vitro invasion, chemotherapy resistance, and in vivo growth and metastasis in an orthotopic model of pancreatic cancer." (PMID 23437065, 2013). "Moreover, BMI1 is related to proliferation, survival, and poor prognosis in pancreatic cancer." (PMID 22539939, 2012). "Research has revealed that high glucose levels can enhance the expression of polycomb protein Bmi1, leading to increased GATA2 levels and suppression of cell surface MICA/B expression, thereby facilitating immune evasion in pancreatic cancer cells." (PMID 38879709, 2024). "BMI1, ALDH1A1, CXCR4, EpCAM, OCT-4, c-MYC, and NESTIN are cancer stemness-related markers of pancreatic cancer." (PMID 35806187, 2022). "Treatment with A-769662 or AICAR increased p-AMPK expression, decreased Bmi1 expression, and increased MICA/B expression in pancreatic cancer cells." (PMID 31088566, 2019). "We further detected the correlation between Bmi1 and MICA/B in pancreatic cancer tissue using immunohistochemistry." (PMID 31088566, 2019). "Our results suggest that STAT3/Bmi1 signaling cascade, which is regulated by ROS-dependent, AKT- or p38-modulated pathways, primarily mediated the sensitivity and motility of pancreatic cancer cells towards combined gemcitabine and VPA regimen." (PMID 31244991, 2019).